ALB (albumin)
Diseases named in the same sentence as ALB in open-access papers (continued):
Sharing a sentence is not in itself a finding about the gene and the disease.
pneumonia (continued). "Lower age, serum albumin and hemoglobin levels, and the presence of comorbidities, hypoxia, severe pneumonia, mechanical ventilation, as well as higher liver injury class (moderate and severe), were associated with increased LOS in the univariate analysis." (PMID 36910412, 2022). "In predicting pneumonia, in addition to serum albumin level, also sex was statistically significant in the model (P = 0.049)." (PMID 35189828, 2022). "Liver damage (decreased albumin and increased globulin) in patients with COVID-19 infections might be associated with the direct effect of the viral infection of liver cells, drug hepatotoxicity, or immune-mediated inflammation, such as cytokine storm and pneumonia-associated hypoxia." (PMID 35677769, 2022). "Considering the feasible measurement from venous blood and the clinical role of RDW on prognosis demonstrated by many studies, the RDW/albumin ratio was applied to evaluate its ability to predict mortality in patients with pneumonia receiving IMV." (PMID 34943582, 2021). "Especially, children with pneumonia with ADV infection had a lower level of albumin (33.386 ± 0.38 g/L) and worse coagulation function (APTT, 43.631 ± 5.89)." (PMID 34869087, 2021). "The correlations of age, age-adjusted Charlson Comorbidity Index (aCCI), basic diseases and nutritional indexes (i.e., albumin, electrolyte, hemoglobin) with pneumonia and prognosis were analyzed." (PMID 34712677, 2021). "The urea-to-albumin ratio (UAR), as a new marker of the systemic inflammatory response, is associated with the mortality in pneumonia patients." (PMID 34721746, 2021). "The RDW/albumin ratio has the potential of a repurposed index to predict the outcome of critically ill patients with pneumonia receiving invasive mechanical ventilation in the ICU." (PMID 34943582, 2021). "Preoperative albumin was reported to correlate inversely with complications such as reintubation, pneumonia, and failure to wean from a mechanical ventilator, especially after upper abdominal surgery." (PMID 34876228, 2021). "The aim of this study was to evaluate the clinical utility of the RDW/albumin ratio regarding 28-day mortality in critically ill patients with pneumonia." (PMID 34943582, 2021). "For another, both LDH and albumin played critical roles in inflammatory responses which was closely related to the development of pneumonia." (PMID 34604286, 2021). "Albumin negatively correlated with the Pneumonia Severity Index (PSI) and CURB-65 scores using Pearson and Spearman tests." (PMID 33662036, 2021). "The present study revealed that the median RDW/albumin ratio was significantly higher in critically ill patients with pneumonia who died at 28 days after receiving IMV." (PMID 34943582, 2021). "LDH and albumin are both easily obtained in routine clinical practice, and both of them were related to pneumonia." (PMID 34604286, 2021). "For T2DM patients adjusted by age, prevalence of severe pneumonia, as well as serum levels of albumin, glucose, and log NT-proBNP, there was a significant contribution of CysC rangeability >0 to all-cause death for men (OR = 4.699, 95% CI: 1.604–13.767)." (PMID 34234738, 2021). "The clinical relevance of the RDW/albumin ratio in critically ill patients with pneumonia that underwent invasive mechanical ventilation (IMV) still remains to be fully elucidated." (PMID 34943582, 2021). "Our data suggest that high RDW/albumin ratio has a similar predictability to the lactate/albumin ratio in critically ill patients with pneumonia receiving IMV." (PMID 34943582, 2021). "The mean hemoglobin and albumin levels were significantly lower in patients with nocardiosis than in patients with pneumonia." (PMID 32868850, 2020). "In our study, a mild decrease in serum albumin also had a significant effect on surgical site infection, pneumonia, septic shock and length of total hospital stay." (PMID 31253199, 2019).
pneumonia (continued). "ASA 4 (p = 0.011), CCI score ≥ 9 (p = 0.042), serum albumin level (p = 0.041), pneumonia (p ≤ 0.001), and overall complications (p = 0.012) had a significant association with 30-day mortality." (PMID 31660937, 2019). "High serum CRP and low serum albumin at the onset of bacteremia are predictive of disease progression to pneumonia and poor prognosis." (PMID 28938875, 2017). "Among 9 patients with both high CRP and low albumin, 5 had pneumonia at the onset of bacteremia and the remaining 4 patients developed pneumonia in a median of 3 days (range, 1 to 8 days) even under effective treatment." (PMID 28938875, 2017). "The fact that patients who developed pneumonia were generally older, and had lower body mass index, serum albumin, and hemoglobin levels than the study cohort overall provides a plausible explanation for these elevated baseline admission rates." (PMID 27955633, 2016). "To determine if LZD differentially altered the course of acute lung injury, we assessed albumin leak as a measure of alveolar permeability in the murine model of post influenza pneumonia." (PMID 25635685, 2015). "The most important determinants of NIV outcome in COPD patients are the presence of pneumonia and the level of serum albumin as an indicator of the patient nutritional status." (PMID 24563868, 2014). "Univariate analysis showed significantly higher SAP II score, Charlson index, prevalence of pneumonia, and lower serum albumin level in the failure group." (PMID 24563868, 2014). "Among them are ageing, gender, dementia, low serum albumin level, low cholesterol level, hyponatremy, complicated pneumonia, cardiovascular diseases, and malignant diseases." (PMID 27785174, 2012). "This measurement is proportional to the extent of the injury in pneumonia and is measured by the leak of a vascular tracer (radiolabeled albumin) in the lung." (PMID 19065261, 2008). "In conclusion, preoperative albumin level is significantly associated with postoperative pneumonia in major non-cardiac surgery patients." (PMID 41200138, 2025). "The increasing trends on the HRs for deaths from all-causes, cancer, CVD, RSD without pneumonia, pneumonia and other-causes with decreasing albumin levels were dose-dependent, especially at lower levels than lower limit of albumin standard value (4.1 mg/dL)." (PMID 41248155, 2025). "Since lactate and albumin independently predict prognosis in pneumonia, the lactate-to-albumin ratio (LAR) may provide a better prognostic performance." (PMID 40346545, 2025). "Increased HRs for death from all-causes, CVD and RSD without pneumonia were also observed in medium albumin group with high gamma gap levels." (PMID 41248155, 2025). "Elevated HRs for deaths from all-causes, cancer, CVD, RSD without pneumonia, pneumonia, and other causes were independently observed in the low/high albumin and gamma gap level groups after adjusting for confounding factors." (PMID 41248155, 2025). "This retrospective cohort study demonstrated that preoperative albumin levels were associated with postoperative in-hospital pneumonia in a non-linear response manner in patients undergoing major non-cardiac surgeries." (PMID 41200138, 2025). "A preoperative albumin level of <45.3 g/L may serve as a predictive marker for postoperative pneumonia." (PMID 41200138, 2025). "Increased HRs for deaths from all-causes, cancer, CVD, RSD without pneumonia, and other-causes were observed in low albumin group with medium and high gamma levels, except other-causes death with medium gamma gap levels." (PMID 41248155, 2025). "The findings of this study suggest that the neutrophil percentage-to-albumin ratio (NPAR) may serve as a prognostic biomarker in pneumonia patients aged 80 years and older admitted to the intensive care unit." (PMID 40364064, 2025). "Further research is needed to determine whether preoperative nutritional interventions aim at raising albumin can reduce the incidence of pneumonia and other postoperative complications." (PMID 41200138, 2025).
pneumonia (continued). "The subgroup analysis among those (n = 20,851) without having history of diseases similarly revealed increased HRs for death from all-causes, CVD, RSD without pneumonia, and other-causes with low albumin levels and with high gamma gap levels." (PMID 41248155, 2025). "HRs for deaths from all-causes and specific causes, such as cancer, CVD, RSD without pneumonia, pneumonia, and other-causes, with the combination of albumin and gamma gap levels were estimated." (PMID 41248155, 2025). "After multivariatelogistic regression, age [OR 1.04 (1.02, 1.06), p < 0.001], pneumonia[OR 2.97 (1.93, 4.57), p < 0.001], D-dimer [OR 1.19 (1.09, 1.31),p < 0.001], and albumin [OR 0.95 (0.91, 0.99), p = 0.009]were identified as independent predictors of an AKI event in hospitalized HFpatients." (PMID 39228491, 2024). "Therefore, a decrease in albumin is a slow process, and if it decreases, it indicates poor immune function and a high likelihood of developing pneumonia." (PMID 39398953, 2024). "Malnourished children with pneumonia had significantly higher values of leukocytes, absolute neutrophilic count, and C-reactive protein, and lower values of hemoglobin, lymphocytic count, platelets, and albumin, compared to controls, respectively." (PMID 37542670, 2023). "In our study, we found that patients with SAP had higher levels of neutrophils than those without, and the neutrophil-to-albumin ratio (NPAR) was associated with an increased risk of pneumonia after ICH." (PMID 37388726, 2023). "In this study, predictors were screened through LASSO logistic analysis, and a prediction model for the risk of acute respiratory failure in elderly patients with hip fracture was constructed based on 7 variables, including age, height, albumin, chloride, pneumonia, AKI, and heparin." (PMID 38007467, 2023). "Furthermore, the reduction of ALB was closely related to increased pulmonary vascular permeability, which has important clinical value in predicting the severity and prognosis of pneumonia." (PMID 37808557, 2023). "Univariate Cox regression analysis revealed that lower agend serum albumin levels, higher incidence of comorbidities, hypoxia, severe pneumonia, mechanical ventilation, as well as higher injury class (moderate and severe), were associated with increased risk of 30-day mortality (all p<0.05)." (PMID 36910412, 2022). "SMART-COP (systolic blood pressure, multilobar infiltrates, albumin, respiratory rate, tachycardia, confusion, oxygen, and pH), developed by a group of Australian academics, is one of the most recent methods for assessing pneumonia." (PMID 36043007, 2022). "In addition, SHAP (SHapley Additive exPlanations) elucidated that a higher proportion of pneumonia and respiratory failure, a higher SOFA score and heart rate, and lower RDW, albumin, serum calcium, and blood pH were risk contributors for developing PerCI." (PMID 36325351, 2022). "Another important modification of HSA that may alter albumin function and influence the severity of symptoms in patients with COVID-19-related pneumonia is related to the creation of MDA-HSA adducts, known as advanced lipoxidation end-products (ALEs)." (PMID 36077496, 2022). "Previous studies showed a high level of albumin might be linked to decreased risk of SAP, and had prognostic value in predicting the risk of pneumonia in AIS patients." (PMID 34604286, 2021). "In T2DM patients adjusted by age, prevalence of severe pneumonia, as well as serum levels of albumin, glucose, and log NT-proBNP, there was a significantly increased contribution of CysC >0.93 mg/dL to all-cause death (OR = 4.059, 95% CI: 1.045–14.340) in women but not in men." (PMID 34234738, 2021). "Considering the role of LDH and albumin in pneumonia, it would be interesting to explore whether a new indicator combing LDH and albumin would show higher value in predicting SAP." (PMID 34604286, 2021). "This study supports the usefulness of the combined index of RDW and albumin in pneumonia." (PMID 34943582, 2021).
pneumonia (continued). "Blood routine testing and blood biochemistry showed that all children with severe pneumonia had a higher lymphocyte count and hemoglobin, and lower albumin, but these three items in cases with adenovirus infection were lower than in cases without adenovirus infection." (PMID 34869087, 2021). "The reduction of serum albumin level is considered to be a biomarker of local and systemic inflammation, and has important clinical value in predicting the severity and prognosis of pneumonia." (PMID 34674642, 2021). "The UAR, novel inflammatory markers, reflect two pathways, which are probably less affected by confounding conditions and may be more predictive in evaluating the prognosis of pneumonia than urea or albumin separately." (PMID 34721746, 2021). "There is a correlation between pneumonia and albumin level in elderly patients." (PMID 34712677, 2021). "The role of serum albumin on pneumonia, relevance to cognitive impairment, and its pathological mechanism remains unknown." (PMID 32049822, 2020). "This suggests that inflammation markers might not be independent prognostic markers when parameters known to influence prognosis, e.g., albumin or BMI, are comprehensively analyzed in patients with pneumonia occurring outside the hospital setting." (PMID 30616612, 2019). "The BUN/ALB level is a simple but an independent predictor of mortality and severity of pneumonia." (PMID 31316681, 2019). "Multivariate analysis confirmed a significant predictive value for pneumonia and albumin." (PMID 24563868, 2014). "Taken together, these results and those of our study suggest that albumin may be a marker of skeletal muscle wasting and an independent factor for predicting life dependency in relatively healthy patients with severe pneumonia and ARDS." (PMID 24723739, 2014). "Interestingly, we also found that a low day 1 albumin level was an independent biomarker for predicting patient life dependence 6 months after a pneumonia event." (PMID 24723739, 2014). "Lee also suggested that albumin was an important prognostic marker for pneumonia." (PMID 23555017, 2013). "Additionally, we aimed to identify the cut-off value of preoperative albumin that could predict postoperative in-hospital pneumonia." (PMID 41200138, 2025). "However, the relationship between preoperative albumin levels and postoperative pneumonia remains unclear in major non-cardiac surgeries, and the cut-off value for predicting postoperative pneumonia has yet to be determined." (PMID 41200138, 2025). "Some clinicopathological features of SCAP patients, such as CRP, ALB, NLR, and NGAL, were reported to possess significant diagnostic or prognostic value in CAP or other types of pneumonia, but their significance was insignificant in the present study, which might result from the small sample size." (PMID 37291525, 2023). "This sudden change in Serum albumin level with rising C-reactive protein in four days immediately after admission in hospital ICU is hallmark of COVID-19 pneumonia which is not seen in other Pneumonias." (PMID 35480533, 2022). "The BUN/ALB ratio could reflect the severity of the patients with pneumonia." (PMID 36522751, 2022). "In addition, children with severe pneumonia had a low level of albumin and a long coagulation time." (PMID 34869087, 2021). "As elevated WBC and depressed albumin are common findings during acute infections, our results could reflect that some patients were discharged too early from the hospital with an on-going pneumonia." (PMID 29600325, 2018). "Baseline serum albumin levels, arterial blood gas measurements, and the proportion of patients who required mechanical ventilation were also similar, which indicates that the overall general health of patients and the severity of pneumonia in these 2 groups were also comparable." (PMID 16965702, 2006).
pneumonia (continued). "Serum albumin and C-reactive protein (CRP) are widely recognized biomarkers for diagnosing and monitoring systemic inflammatory conditions, including pneumonia." (PMID 40248251, 2025). "Conversely, the mild to moderate pneumonia group exhibited significantly higher levels of age, weight, PLT, HCT, HGB, TP, ALB, GLOB, and ALP compared to the severe pneumonia group." (PMID 40529154, 2025). "Model 3: include adjustments for age, gender, ethnicity, respiratory rate, heart rate, MAP, AMI, pneumonia, GCS score, creatinine, albumin, WBC, hemoglobin." (PMID 40670661, 2025). "We also used AUROC of other inflammatory markers to predict the incidence of pneumonia, 0.61 for admission LDH levels, 0.53 for glucose, 0.56 for leukocytes, 0.61 for lymphocytes, 0.67 for albumin, and 0.53 for platelets." (PMID 38404841, 2024). "Additionally, we discovered that factors such as duration of bed rest, unplanned re-operation, ETCO2, postoperative albumin, chest X-ray film, vasoactive agent, age, duration of ventilation, ASA physical status, and postoperative hemoglobin were closely associated with postoperative pneumonia." (PMID 39726646, 2024). "IL-6, WBC, L, N, CRP, PCT, PT, DD, BS, AST, ALB, D-Bil, BNP, LDH, and CK-MB differed significantly between moderate and severe pneumonia sets both in training and validation sets (P < 0.05)." (PMID 37950171, 2023). "The degree of dysphagia was the primary outcome indicator, with secondary outcomes including serum albumin (ALB) and hemoglobin (Hb) levels, the incidence of pneumonia, and adverse events." (PMID 37305760, 2023). "Between the two groups, we found significant differences in gender, history of suffering from pneumonia, MMSE, current smoking status, leg extension force, total cholesterol level, and serum albumin level." (PMID 37176712, 2023). "In the training group, the LASSO logistic regression along with the 10-fold cross-validation identified eight predictors, including admission albumin, serum calcium, RDW, blood pH, heart rate, respiratory failure, pneumonia, and SOFA." (PMID 36325351, 2022). "Our study demonstrated that the development of pneumonia in mechanically ventilated patients (VAP) depends on numerous factors, including multi-organ injury, albumin and leucocytes levels, the CRP value, an age over 61 years, and the male gender." (PMID 35010870, 2022). "During an episode of pneumonia (at 1 y 3 mo) in the ICU, she was given several albumin infusions, and every time she developed a fever after a few hours." (PMID 34073526, 2021). "The baseline clinical characteristics were not significantly different except the degree of inflammation (lower albumin and higher CRP) in patients with GS, pneumonia, and intubation." (PMID 33147270, 2020). "To date, many studies have reported various prognostic factors for CAP, including the pneumonia severity index (PSI), PCT, albumin, body mass index (BMI), and brain natriuretic peptide (BNP) or N-terminal-proBNP (NT-proBNP)." (PMID 30616612, 2019). "The results showed that body temperature, cough, sputum, nausea and vomiting, WBC, CK-MB, ALB, and AST were significantly different between the PQ poisoning and pneumonia." (PMID 31636276, 2019). "Inflammation and lung leakage, both markers of pneumonia, were examined by assaying myeloperoxidase (MPO) activity, a measure of neutrophil numbers, and albumin level respectively in the bronchoalveolar lavage (BAL) fluid collected from the mice." (PMID 28074841, 2017). "Among allo-HSCT recipients with S. maltophilia bacteremia, low albumin and high CRP levels appear to be predictive of disease progression to pneumonia and poor prognosis." (PMID 28938875, 2017). "Coating of polystyrene plates with Human serum albumin (HSA) was found to significantly reduce bacterial adhesion and biofilm formation in S. pneumonia." (PMID 28155216, 2017). "The results revealed a non-linear dose–response relationship between preoperative albumin levels and postoperative pneumonia." (PMID 41200138, 2025).